CA6 (carbonic anhydrase 6)
Description:
Reversible hydration of carbon dioxide. Its role in saliva is unknown.
Synonyms: CA-VI; GUSTIN
Tractability: Small molecule: an approved drug acts on it; a high-quality ligand is known; it belongs to a druggable protein family. Antibody: its Gene Ontology location is reachable by antibodies, with high confidence; UniProt places it where antibodies can reach, with medium confidence; UniProt predicts a signal peptide or a membrane-spanning region. PROTAC: a small molecule that binds it is known.
Target class: Enzyme; Lyase
Gene: Protein-coding gene on chromosome 1 (8,945,867 to 8,975,092, forward strand). Ensembl gene ENSG00000131686.
Subcellular location: Secreted
Pathways (Reactome):
Metabolism: Reversible hydration of carbon dioxide
Gene Ontology:
Molecular function: carbonate dehydratase activity; zinc ion binding
Biological process: detection of chemical stimulus involved in sensory perception of bitter taste
Cellular component: extracellular exosome; extracellular region; cytoplasm; cytosol
Genetic constraint (gnomAD): Loss-of-function variants: 21 observed, 24.82 expected, observed/expected ratio (o/e) 0.85, 90% interval 0.6 to 1.22. The upper end of that interval is the gene's LOEUF score, 1.22, which puts it in group 5 of 6, group 1 being the genes least tolerant of losing a copy. Missense variants: 287 observed, 301.58 expected, observed/expected ratio (o/e) 0.95, 90% interval 0.86 to 1.05. Synonymous variants: 120 observed, 124.26 expected, observed/expected ratio (o/e) 0.97, 90% interval 0.83 to 1.12.
Homologues: Orthologues: chimpanzee CA6 (90% identical), macaque CA6 (86% identical), dog CA6 (75% identical), pig CA6 (72% identical), rat Car6 (56% identical), zebrafish ca6 (53% identical), mouse Car6 (52% identical), tropical clawed frog ca6 (47% identical), Drosophila melanogaster CAH6 (29% identical), Drosophila melanogaster CAH16 (27% identical), Drosophila melanogaster CAH4 (27% identical), Drosophila melanogaster CAH8 (27% identical), and 10 more. Paralogues in human: CA9 (38% identical), CA14 (35% identical), CA12 (35% identical), CA7 (31% identical), CA4 (29% identical), CA13 (28% identical), CA2 (28% identical), CA3 (28% identical), CA5A (28% identical), CA8 (27% identical), CA1 (26% identical), CA5B (26% identical), and 2 more.